Y_RNA (Y RNA )
Gene: Miscellaneous RNA gene on chromosome 20 (23,457,584 to 23,457,685, reverse strand). Ensembl gene ENSG00000200208.
Homologues: Orthologues: chimpanzee Y_RNA (97% identical), macaque Y_RNA (95% identical), tropical clawed frog Y_RNA (75% identical). Paralogues in human: RNY3 (89% identical), Y_RNA (88% identical), Y_RNA (87% identical), RNY3P1 (86% identical), Y_RNA (86% identical), Y_RNA (85% identical), RNY3P11 (84% identical), Y_RNA (84% identical), RNY3P16 (83% identical), RNY3P3 (83% identical), Y_RNA (83% identical), RNY3P9 (82% identical), and 94 more.